BRAF (B-Raf proto-oncogene, serine/threonine kinase)
Diseases named in the same sentence as BRAF in open-access papers (continued):
Sharing a sentence is not in itself a finding about the gene and the disease.
thyroid cancer (continued). "A few studies on thyroid cancer tissues have found expression of CAF-related proteins in thyroid cancer stroma, and have revealed that certain CAF-related protein expression is related with cervical lymph node metastasis, histologic subtype, BRAF mutation, and prognosis." (PMID 36293435, 2022). "In PDX models of colorectal and thyroid cancers, we observed significant inhibitory effect of the combination of selumetinib and KRT-232 on tumor growth across a spectrum of MAPK genomic backgrounds, including BRAF, KRAS, and NRAS mutations, compared to single-agent treatment with either drug." (PMID 35075200, 2022). "However, more than 10% of thyroid cancers are wild-type BRAF, and these tumors may be more aggressive, as they have been reported to harbor chromosomal aberrations." (PMID 36313748, 2022). "In addition, we found that BRAF and NF1 mutations are two of the main regulators in Chinese PTC patients, and they play critical but different roles in regulating the development of thyroid cancer." (PMID 35865459, 2022). "In addition, BRAF mutations are closely related to poor prognosis of tumors, and it is currently a hot topic of research on combining BRAF mutation testing and FNA to improve the accuracy of thyroid nodule diagnosis and effectively identify people at high risk of thyroid cancer." (PMID 36160023, 2022). "Besides these evidences, whether MDSCs and other types of immune cells are recruited into thyroid cancer microenvironment, and, if so, what pathological roles they are playing, or how activated BRAF/MAPK pathway regulates this process, remains to be explored." (PMID 35332119, 2022). "Interestingly, DLCs induced redifferentiation with enhanced NIS expression in several thyroid cancer cell lines irrespective of mutations such as BRAF, PTEN loss, or RET/PTC rearrangement." (PMID 33995657, 2021). "In this study we tested whether BRAF and/or TERT promoter mutations conferred sensitivity to YK-4-279 in thyroid cancer cells and whether this inhibitor could be served as a therapeutic agent for advanced thyroid cancers." (PMID 34221969, 2021). "Therefore, targeting BRAFV600E could be the most promising treatment among patients with BRAF mutant (BRAFMT) thyroid cancer." (PMID 33468157, 2021). "Thus, we hypothesized that it might be possible to improve the response of BRAF V600E-positive thyroid cancer cells to MEK inhibitors by increasing RAC1 activity." (PMID 34831012, 2021). "In particular, a close association of BRAF mutation with extrathyroidal extension, lymph node metastasis, and advanced TNM stages III/IV of PTC, which are well-documented risk factors associated with increased rates of recurrence and mortality of thyroid cancer, have been reported." (PMID 33572167, 2021). "Since it is reported in literature that the leptin effects are mediated by MAPK signaling pathway in thyroid cancer, here we evaluated whether the pharmacological inhibition of BRAF impairs the combined effects of the two adipokines on thyroid cancer cell proliferation." (PMID 33587254, 2021). "We found a nodule mutated for BRAF with negative histology for thyroid cancer." (PMID 33716969, 2021). "Numerous studies have demonstrated that TERT promoter mutations, especially when accompanied with BRAF V600E or RAS mutations, showed strong correlation to aggressive clinical characteristics, radioiodine refractory and poor clinical outcomes in patients with thyroid cancer." (PMID 34221969, 2021). "Similarly, Au-si-CYP2S1 selectively inhibited cell proliferation in BRAFV600E-mutated thyroid cancer cells, but not in BRAF wild-type ones." (PMID 32913191, 2020). "There were no RAS mutation in the 13 BRAF V600E positive thyroid cancers." (PMID 31758407, 2020). "However, BRAF also has been reported to mutate in benign thyroid nodules and is not suitable for early diagnosis of thyroid cancer." (PMID 32428871, 2020).
thyroid cancer (continued). "A recent study reported that fibroblast growth factor receptors (FGFRs) may activate RAS in a SHP2-independent manner in BRAF mutant colon and thyroid cancer cells in the setting of pathway feedback activation following treatment with BRAF inhibitors such as vemurafenib." (PMID 32076487, 2020). "Considering thyroid cancer, one of the most important consequences of the new era of genomic studies is the possibility to differentiate between the two genetic types, particularly the manner in which BRAF and RAS signaling promotes tumor development and growth." (PMID 31312183, 2019). "Literature data have shown low frequency of BRAF mutations in distant metastases, in comparison with the paired primary tumours, thus suggesting that this mutation could play a role in thyroid cancer initiation but not progression." (PMID 29716526, 2018). "In thyroid cancer, BRAF pseudogene expression is negatively associated with BRAF mutation because the pseudogene transcripts are more frequently detected in tumors without BRAF mutation than those with BRAF mutation." (PMID 30071685, 2018). "The presence of BRAF mutation in BCPAP and SW1736 can aberrantly activate HIF pathway independent of hypoxia, promoting overactive MEK/EPK signalling which results in increased HIF protein synthesis, suggesting that activation of the HIF pathway is essential in thyroid cancer progression." (PMID 29167950, 2018). "Sporadic thyroid cancers usually develop via abnormal activation of the RAS-RAF-MEK-ERK signaling pathway (MAPK; which relays signals from cell membrane to nucleus), primarily as a result of point mutations in the RAS/BRAF genes or chromosomal rearrangements such as RET/PTC translocations." (PMID 30086162, 2018). "In addition to BRAF, RET mutations are also responsible for thyroid cancers." (PMID 29629339, 2018). "The initiation of thyroid cancer is often triggered by a genetic mutation in the phosphortidylinositol-3 kinase (PI3K) or mitogen-activated protein kinase (MAPK) pathway, such as RAS and BRAF, or by the rearrangement of growth factor receptor tyrosine kinase genes such as RET/PTC." (PMID 29163356, 2017). "MAPK rebound caused by BRAF/MEK inhibitors-induced activation of HER2/HER3 is a resistance mechanism, and combination with HER inhibitor to prevent MAPK rebound may sensitize BRAFV600E-mutant thyroid cancer cells to redifferentiation therapy." (PMID 28423638, 2017). "The discordant results of these two studies looking into the clinical significance of sub-clonality for BRAF mutation in thyroid cancer might be the result of lack of correction for tumor cell fraction in each sample." (PMID 28501852, 2017). "The data in the present study are consistent with a model in which BRAF V600E-activated MAPK pathway causes hypomethylation of the WIPF1 promoter, hence resulting in over-expression of WIPF1, which in turn promotes the invasiveness and aggressiveness of thyroid cancer." (PMID 27863429, 2017). "Although BRAF mutation is negative, the lymph node metastasis may be attributed to the aggressive behavior of the thyroid cancer in GD." (PMID 27110424, 2016). "In conclusion, the results of the present study indicate that IFNγ, among its pleiotropic effects, is also able to inhibit CXCL8 secretion and cell migration in BRAF V600e mutated BCPAP but not in TPC-1 thyroid cancer cell line bearing the RET/PTC rearrangement." (PMID 27555670, 2016). "Vemurafenib, a selective BRAF inhibitor, could effectively be used in treating PTC with BRAFV600E mutation, suggesting that reduction in the activity of MAPK pathway by inhibiting BRAF is effective for treating thyroid cancer." (PMID 26985248, 2016). "On the contrary, the most common genetic abnormality in papillary thyroid carcinoma BRAF mutation appears to be absent in FAP associated thyroid cancer, suggesting that BRAF and APC RET/PTC mutations are mutually exclusive of each other in the occurrence of different types of PTC." (PMID 26697262, 2015).
thyroid cancer (continued). "There are not so many publications about the BRAF mutation in paediatric thyroid carcinomas." (PMID 26584635, 2015). "Additionally, the mutation of the gene BRAF in RTK-RAS pathway could be found in CRC, although it was frequently mutated in thyroid carcinoma." (PMID 25617745, 2015). "Thyroid cancers frequently harbor activating mutations in the mitogen-activated protein kinase (MAPK) and phosphatidylinositol 3-kinase (PI3K)/Akt signaling pathways, as represented by RET/PTC, RAS and BRAF mutations in the former and by PIK3CA and PTEN mutations in the latter." (PMID 24137342, 2013). "Studies have shown that sorafenib can inhibit proliferation of poorly differentiated thyroid cancer cell lines regardless of whether they harbor BRAF V600E mutations." (PMID 22654559, 2011). "Moreover, a significant incidence of BRAFV600E mutation has been found in undifferentiated thyroid cancers, suggesting that ATC may arise from more typical forms of PTC and that BRAF signalling may be functionally relevant in tumor progression." (PMID 19578508, 2008). "Overall, the clonal nature and mutual exclusivity of genetic alterations in BRAF, RAS, RET, and other key genes indicate that a single genetic change is the primary initiating event in most thyroid cancers, with impressive genotype–phenotype correlation." (PMID 41175860, 2025). "Selective BRAF and MEK inhibitors – including vemurafenib, dabrafenib, and selumetinib – have demonstrated efficacy in advanced thyroid cancers." (PMID 41368991, 2025). "With targeted degradation of FAK, we found an effective decrease in total FAK protein within 4 hours of FAK PROTAC treatment and a corresponding decrease in pY397 FAK expression in 24 hours in BRAF-mutant, KTC1 and KTC2, thyroid cancer cells." (PMID 40458728, 2025). "The results revealed significant increases in the expression of BRAF, EIF1 AX, KRAS, PIK3 CA, and TERT genes across all types of immune cells in thyroid cancer, indicating their variability and potential regulatory roles in the immune microenvironment." (PMID 40450370, 2025). "In BRAF-mutant thyroid cancer, NG2 contributes to resistance against BRAF inhibitors by sustaining alternative growth signaling pathways, particularly through RTK signaling." (PMID 39874138, 2025). "Analysis of single-cell sequencing data revealed that BRAF, EIF1 AX, KRAS, PIK3 CA, and TERT are significantly up-regulated in various immune cells within thyroid cancer, underscoring their potential regulatory roles in the immune microenvironment." (PMID 40450370, 2025). "Targeted agents such as BRAF and MEK inhibitors have shown positive therapeutic effects in some patients with RAI-R thyroid cancer by restoring the uptake capacity of radioactive iodine." (PMID 41462994, 2025). "Further research identified a feedback loop in thyroid cancer cells, where RAF and MEK inhibition led to HER3 upregulation, ultimately reactivating the MAPK pathway and limiting the sustained effects of BRAF inhibition." (PMID 41368991, 2025). "We found that a fraction of pY397 FAK co-localizes with the nucleolar marker, FBL, in the panel of BRAF- and RAS-mutant thyroid cancer cell lines derived from PTC or ATC tumors." (PMID 40458728, 2025). "Subsequently, BRAF/MEK inhibitors, RET inhibitors and TRK inhibitors were approved for advanced thyroid carcinoma." (PMID 40275967, 2025). "The next-generation IHC for BRAF V600E, RAS Q61R, pan-TRK, ALK, PTEN, and β-catenin has promising roles in the diagnosis and molecular classification of thyroid carcinomas." (PMID 40111709, 2025).
thyroid cancer (continued). "Nevertheless, it has been noted that thyroid cancers with BRAF pathogenic variants tend to respond less favorably to redifferentiation therapies, suggesting that a stronger inhibition of the MAPK pathway may be necessary, potentially through a dual therapy of BRAF and MEK inhibitors." (PMID 39685621, 2024). "Here, we assess growth and signaling responses to combined BRAF and MEK1/2 inhibition in a panel of BRAF-mutant thyroid cancer cell lines." (PMID 38521968, 2024). "However, BRAF mutations and RET and NTRK fusions, major markers for molecularly targeted therapies in thyroid carcinoma, are considered early molecular events in thyroid carcinogenesis, which may indicate their presence in lymph node metastases similar to their primary lesions." (PMID 39560912, 2024). "As in eutopic thyroid gland carcinomas, the most common genetic alterations in MSO are BRAF abnormalities." (PMID 38396644, 2024). "We could not find the gene expression data for HLA-E and thyroid cancer with BRAF mutation in other studies, but HLA-E and HLA-F expression significantly correlated with depth of invasion, nodal involvement, lymphatic invasion, and venous invasion in gastric cancer patients." (PMID 36975440, 2023). "Sorafenib is of specific interest in thyroid cancer as it targets the Raf-family kinases (RAF-1 and BRAF) in addition to VEGFR, PDGFR and RET." (PMID 38076095, 2023). "In BRAF mutant thyroid cancers, treatment with PAK kinase inhibitor G-5555 reduces thyroid cancer cell progression." (PMID 36830998, 2023). "The treatment landscape for thyroid cancers has changed rapidly with the availability of kinase inhibitors against VEGFR, BRAF, MEK, NTRK, and RET." (PMID 37434642, 2023). "We have previously demonstrated that combined inhibition of Src with dasatinib and the MAPK pathway with trametinib synergistically inhibits growth and induces apoptosis in BRAF- and RAS-mutant thyroid cancer cells." (PMID 36672327, 2023). "Alterations in the MAPK [MAPK kinase (MEK)/ERK] signaling pathway, such as mutant BRAF, RAS, and RET fusions represent the majority of alterations in differentiated thyroid cancers and are key drivers in the progression of disease." (PMID 37191938, 2023). "The oncogenes activated in thyroid carcinomas, RET/PTC, RAS, and BRAF, by triggering the MAPK cascade, can induce a proinflammatory transcriptional program in thyrocytes, which mainly includes cytokines, chemokines, and their receptors." (PMID 37959281, 2023). "Evaluation of thyroid FNAs with the Unified Assay identified all fusion proteins described for thyroid cancer in TCGA, the most common fusion pair being PAX8-PPARg, with other common fusion partners including RET, NTRK1/3, ALK, and BRAF." (PMID 36675685, 2022). "New drug strategies, such as combining BRAF or MEK inhibitors with pan-PI3K inhibitors, are beginning to show pre-clinical promise in thyroid cancer." (PMID 34520744, 2022). "It has recently been shown to play an important role in thyroid cancer, with related genes, such as RET/PTC, RAS, and BRAF, acting through NF-κB." (PMID 36675746, 2022). "In addition, LOX upregulation is also associated with anaplastic thyroid cancer progression and aggressive tall cell variant of PTC (TC-PTC) compared with the differentiated thyroid cancers [classic PTC (cPTC) and follicular variant of PTC (FV-PTC)] that may respond to BRAF activation." (PMID 36120433, 2022). "However, the most recent American Thyroid Association (ATA) recommendations do not indicate a routine application of BRAF status for initial risk stratification in differentiated thyroid cancer due to a lack of evident confirmation of a direct influence of mutation on the increase in relapse risk." (PMID 34345541, 2021).
thyroid cancer (continued). "BRAF inhibitors, histone modification inhibitors, MEK and MAPK inhibitors promote apoptosis of thyroid cancer cells." (PMID 34923978, 2021). "This was further confirmed by comparing the gene expression profiles between BCPAP cells and human thyroid cancer tissues (series GSE104005) previously established by our laboratory and classified for the BRAF- or RAS-like signaling subtype." (PMID 34072194, 2021). "A study by Chakravarty and collaborators demonstrated that BRAF and MEK inhibitors were able to restore RAI uptake in mouse thyroid carcinomas turned refractory to iodide by the conditional activation of BRAF." (PMID 34831012, 2021). "It has also been demonstrated that the co-existence of BRAF/RAS and TERT genetic alterations has a detrimental impact on the aggressiveness of thyroid carcinoma." (PMID 34830540, 2021). "Based on previous reports, there are currently several biomarkers that have clinical implications for thyroid cancer including RET/PTC, RAS, BRAF, PAX8-PPARγ, MicroRNAs (miR-221, 222, and 181b), and activation of telomerase reverse transcriptase (TERT)." (PMID 33247684, 2020). "Targeted treatment with BRAF and MAPK inhibitors have been shown to re-sensitize thyroid cancer cells/tumors to RAI therapy by improving NIS expression." (PMID 32751138, 2020). "In the molecular diagnosis of thyroid cancer, the related molecular markers include TERT, BRAF, PAX8/ PPARγ, RAS and RET/PTC26." (PMID 31949496, 2020). "Recently, the FDA approved two small BRAF-specific inhibitors: vemurafenib and dabrafenib for BRAFV600E-positive advanced RAI-refractory thyroid cancer and metastatic PTC." (PMID 32748840, 2020). "Many somatic genetic alterations, including those in BRAF, HRAS, KRAS, NRAS, PTEN, and HER1, have had fundamental roles in the tumorigenesis of thyroid carcinoma." (PMID 31655978, 2020). "The discovery of oncogenes that drive thyroid cancer (such as RET, RAS, and BRAF), and are aligned in the MAPK/ERK pathway has led to a new perspective of thyroid oncogenesis." (PMID 31482959, 2019). "Among these proteins, BRAF and MAP2K1 were affected by phosphorylation in early-stage thyroid cancer cells." (PMID 31126066, 2019). "In thyroid carcinoma (THCA), 5.23% were BRAF p.V600E, 0.65% were NRAS p.Q61R, and 0.25% HRAS p.Q61R." (PMID 30890735, 2019). "In addition, it is still not known whether thyroid cancer in acromegalic patients is associated with genetic events such as the BRAF V600E mutation." (PMID 29593792, 2018). "Compared to BRAF wild-type BHP 2-7 cells, BRAF inhibitor dabrafenib preferentially inhibited ERK signaling and thyroid cancer cell proliferation, arrested cell circle, and regulated iodine and glucose-handling gene expression in BRAFV600E-positive PTC cells." (PMID 28423638, 2017). "Furthermore, it was reported that in thyroid cancer cells (harbouring BRAFV600E mutation) BAG3 can regulate cell growth both in vitro and in vivo and the underlying molecular mechanism appears to rely on BAG3 binding to BRAF, that protects BRAF from proteasome-dependent degradation." (PMID 29113311, 2017). "Mutations in key signaling effectors of the mitogen activated protein kinase (MAPK) pathway, including BRAF and RAS, are found in 70% of thyroid cancers." (PMID 28350298, 2017).